CRP (C-reactive protein)
Diseases named in the same sentence as CRP in open-access papers (continued):
Sharing a sentence is not in itself a finding about the gene and the disease.
cancer (continued). "Our results are in line with previous reports on CRP in cancer, where high CRP serum concentrations were associated with more aggressive tumor behavior, higher tumor stages and poor outcome." (PMID 28514756, 2017). "In the normal population, 70%–90% of samples have a CRP concentration of less than 0.3 mg/dl, while serum CRP levels in cancer patients are significantly higher and linked with tumor burden and disease progression." (PMID 29262550, 2017). "Some studies have reported that various biomarkers, such as TNF-alpha, interleukin (IL)-1 beta, IL-6, IL-2, CRP, etc., are associated with cancer-related fatigue, although the results of these studies are not consistent in regarding this issue." (PMID 28679410, 2017). "Elevated blood CRP, a biochemical marker of inflammation, can be used to help detect cancer-related nutrition problems that predispose to poor outcomes." (PMID 29108370, 2017). "GPS and mGPS were thus generalized from the combination of CRP and albumin; as new inflammatory markers, they have been proved to be useful prognostic factors to predict the risk of cancer." (PMID 28676731, 2017). "More and more studies demonstrated that serum CRP is associated with prognosis in several cancers, including EC." (PMID 28968977, 2017). "Given that cancer is related to several forms of inflammation, CRP levels have also been implicated." (PMID 28706007, 2017). "The ratio of C-reactive protein to albumin, as a novel inflammation-based prognostic score, is associated with outcomes in cancer and septic patients." (PMID 28069031, 2017). "These shared biological mechanisms between CVD and cancer naturally suggest some common diagnostic biomarkers, such as the elevation of C-reactive protein (CRP), which is a biomarker for inflammation." (PMID 29258216, 2017). "We report an association between inflammatory markers IL-6 and CRP and appetite, and IL-1ra and fatigue in cancer patients with advanced disease." (PMID 28542626, 2017). "The Glasgow Prognostic Score (GPS) combines albumin and CRP into a risk stratification score for the prognosis of clinical outcome in cancer patients." (PMID 28717855, 2017). "The goal of this meta-analysis was to comprehensively examine the relationship between the two CRP SNPs and cancer susceptibility." (PMID 26912098, 2016). "Future research is quite necessary to provide compelling evidence of the association between CRP gene polymorphisms and cancer risk." (PMID 26912098, 2016). "After title and abstract evaluation, 127 articles were removed due to non-cancer studies or polymorphism studies irrelevant to CRP SNPs." (PMID 26912098, 2016). "This meta-analysis summarized a total of 8 case-control studies, providing evidence that supported a significant role of CRP polymorphisms in cancer." (PMID 26912098, 2016). "Univariate analysis demonstrated a significant association between high levels of serum CRP and adverse cancer-specific survival (P = 0.001) and recurrence-free survival (P < 0.001)." (PMID 27733196, 2016). "We investigated the associations of C-reactive protein (CRP) and leukocyte count with cancer risk and mortality using individual biomarkers, and an inflammatory score derived from both biomarkers." (PMID 26860264, 2016). "In conclusion, we found that genetic polymorphisms in the CRP gene, +942G>C and 1846C>T, are associated with an increased overall risk of cancer." (PMID 26912098, 2016). "Smoking is associated with changes in CRP concentrations and is thus an important confounder when relating CRP to cancer risk or mortality." (PMID 26860264, 2016). "Multivariable Cox regression was used to assess leptin and CRP levels (low, moderate, high) in relation to risk of cancer death." (PMID 26632325, 2016). "Elevated vitamin B12 was also found to be a predictor of LOS independent of age, gender, BMI, six-month previous unintentional weight loss, admission ward, presence of malignancy, renal function, C-reactive protein and prealbumin (p = 0.027)." (PMID 28025528, 2016).
cancer (continued). "Recently, several previous studies have shown that CRP is associated with prognosis in several cancers, including ECs." (PMID 27212808, 2016). "Published data indicate that relating a single measurement of CRP to cancer risk underestimates the true strength of the association." (PMID 26860264, 2016). "C-reactive protein and leukocyte counts are biomarkers of systemic inflammation that have been related to all-cause cancer and cancer mortality in previous studies." (PMID 26860264, 2016). "Blood biomarkers, such as neutrophil count, monocyte count, platelet count, serum C-reactive protein level, serum albumin level, and interleukin-6 level, for the systemic inflammatory response are associated with cancer prognosis." (PMID 27732629, 2016). "The corresponding results for CRP were (RR = 1.23, 95 % CI 0.97-1.55) for risk and (RR = 1.15, 95 % CI 0.81-1.64) for cancer mortality." (PMID 26860264, 2016). "In patients with cancer, low plasma vitamin C levels (<11 μmol/L) are associated with increased inflammatory activity (raised C-reactive protein (CRP) levels), poor nutritional condition (low albumin levels), and a shorter survival time." (PMID 26985904, 2016). "From the competing risk analysis where we took into account competing outcomes, it was further suggested the inverse association between serum leptin and cumulative mortality from cancer in women, and a positive association for CRP in men." (PMID 26632325, 2016). "There were positive associations between CRP, leukocyte count, and cancer risk, which were attenuated after adjustment for smoking." (PMID 26860264, 2016). "Elevated levels of C-reactive protein (CRP) partially induced by polymorphisms in the CRP gene have been associated with human cancer." (PMID 26912098, 2016). "We systematically identified the publications addressing the association of CRP gene polymorphisms with cancer susceptibility." (PMID 26912098, 2016). "Patients with cancer with CRP levels above the obtained cutoff value have a higher risk of tumor recurrence and cancer-related death than cases with levels below the value." (PMID 27733196, 2016). "To elucidate on the associations of inflammatory biomarkers with cancer, we investigated the associations of CRP and leukocyte count with cancer risk and mortality independently, as well as using a derived biomarker z-score combining both biomarkers." (PMID 26860264, 2016). "Higher levels of post-diagnosis CRP have been linked with worse survival in various malignancies, including BCa, suggesting the importance of inflammation in cancer progression." (PMID 27294662, 2016). "An association of CRP and a higher risk of death were seen in several cancers such as lymphoma, multiple myeloma, esophageal carcinoma, and colorectal cancer." (PMID 27091202, 2016). "Regarding other specific causes of mortality, higher CRP concentrations at baseline were associated with greater risk of cancer mortality (HR 1.62, 1.13–2.33, p = 0.009)." (PMID 26039142, 2015). "Increasing age, male gender, hospital admission, history of cancer, high C-reactive protein (>3mg/l) and neutrophil counts were independently associated with an increase in cardiovascular mortality (all p<0.001)." (PMID 25730322, 2015). "The lack of association between inflammatory markers and specific cancer risk was further shown when we investigated serum CRP, leukocytes, albumin, and haptoglobin in relation to prostate cancer." (PMID 26284119, 2015). "Increasing age, male gender, history of cancer, high C-reactive protein (>10mg/l), neutrophil and platelet counts were independently associated with an increase in cancer specific mortality (all p<0.001)." (PMID 25730322, 2015). "Accumulating evidence indicates that polymorphisms in the CRP gene are important in the development of cancer." (PMID 25624919, 2015).
cancer (continued). "Increasing age, hospital admission, history of cancer, high C-reactive protein (>3mg/l) and neutrophil counts were independently associated with an increase in cerebrovascular mortality (all p<0.05)." (PMID 25730322, 2015). "It is noteworthy that a recently published study of 270,000 hospital patients, showed that high CRP levels not only predicted all-cause mortality (compared to the low/or normal CRP group), but also higher cancer mortality." (PMID 26717416, 2015). "Accordingly, the serum level of C-reactive protein, a well-known inflammation marker, was associated with increased risk of some cancers according to recent meta-analyses." (PMID 26442127, 2015). "As C-reactive protein, albumin and neutrophils were consistently predictive of all-cause, cancer, cardiovascular and cerebrovascular specific mortality, these were taken forward to examine the prognostic value of their combination." (PMID 25730322, 2015). "Previous studies have investigated the association between CRP 3407A>G and 29A>T polymorphisms, and cancer risk." (PMID 25624919, 2015). "These associations were also observed in cancer, cardiovascular and cerebrovascular mortality before and after the introduction of high sensitivity C-reactive protein measurements (>3mg/l) (n = 52 091)." (PMID 25730322, 2015). "Among individuals diagnosed with cancer, patients with a high baseline CRP (>3 mg/L) had an 80% greater risk of early death versus those with low CRP levels (<1 mg/L)." (PMID 26339617, 2015). "The incorporation of CRP and albumin levels allow to take into account the effects of systemic inflammation and the progressive nutritional decline associated with advanced cancer." (PMID 26496339, 2015). "The current meta-analysis was performed to investigate the association between CRP polymorphisms 3407 A>G (rs2808630) and 29 A>T (rs1417938), and the risk of developing cancer." (PMID 25624919, 2015). "A simple inflammation-based scoring system, combining C-reactive protein and serum albumin, is associated with prognosis in patients undergoing cancer treatments." (PMID 26072055, 2015). "In our study, we performed logistic regression analysis using high levels of CRP (>3 mg/ml indicating increased risk of any type of cancer) as the dependent variable." (PMID 26380255, 2015). "When patients were stratified by cancer stages, a high level of CRP-SAA was also associated with a shorter median survival in the stages I–II and stages III–IV subgroups." (PMID 26264146, 2015). "The magnitude of the increase in CRP levels has been associated with poor survival in cancer, particularly in patients with advanced stage disease." (PMID 24718309, 2014). "The high recurrence and pervasiveness of the CRP-286 SNP mutations in tumors suggest that locally produced CRP, instead of circulating CRP, drives the development of cancer." (PMID 25025473, 2014). "CRP is a sensitive marker of systemic inflammation, and elevated CRP concentrations are associated with poorer survival in cancer patients, particularly in patients with advanced disease." (PMID 24885814, 2014). "As a result, the exact underlying role of CRP in various types of cancer including CRC requires more biological exploratory studies in the future." (PMID 24255664, 2013). "In conclusion, we have shown that an elevated preoperative serum CRP level is significantly associated with reduced cancer-specific survival." (PMID 23642165, 2013). "Elevated plasma CRP levels are not only associated with an increased risk of cancer but also have been linked to advanced disease with poor prognosis in various malignancies." (PMID 24148787, 2013). "The subjects with highly elevated CRP concentrations have a three-fold elevation “all-cause” mortality risk and a twenty-eight fold increase in cancer mortality risk." (PMID 23947403, 2013).
cancer (continued). "This study employed a large European cohort of 10,215 subjects and demonstrated an insignificant odds ratio for cancer associated with doubling of CRP level of 0.94 (95% CI of 0.81 to 1.08)." (PMID 23369448, 2012). "Lastly, we tested the association of patient survival with CRP values against that with other established clinical and biochemical parameters, including the Memorial Sloan-Kettering Cancer Center (MSKCC) risk factors." (PMID 22857740, 2012). "Elevated levels of CRP were positively associated with increased BC risk and risk of cancer death, and they were positively correlated with SUA levels in early and advanced stages of BC." (PMID 23369448, 2012). "Elevated CRP levels can be a result of an underlying cancer and a premalignant state, respectively, as well as due to tumour growth associated tissue inflammation." (PMID 22958305, 2012). "High CRP levels are common in patients with advanced disease, because advanced cancer is often associated with an inflammatory response." (PMID 22103888, 2011). "CRP is a representative marker for inflammatory conditions and it has been reported that the risk of cancer is increased when pre-diagnostic CRP levels are high." (PMID 21811552, 2011). "Raised CRP concentrations at the time of admission to hospital are indicative of an increased risk for all-cause mortality; there is a 22.8-fold increase in cancer mortality in patients with highly elevated CRP concentrations (>80 mg/L)." (PMID 21760776, 2011). "On multivariate analysis, the associations with the presence of cancer remained with age, deprivation, C-reactive protein, albumin, adjusted calcium, Alk phos and GGT (all P<0.01)." (PMID 20717110, 2010). "Some authors have observed an association between elevated serum CRP levels in some cancers, like colorectal and lung." (PMID 20673375, 2010). "In the non-cancer cohort the strongest associations (Spearman's correlation ⩾0.3) were between C-reactive protein and albumin, C-reactive protein and Alk phos, AST and ALT, AST and GGT and ALT and GGT." (PMID 20717110, 2010). "On multivariate analysis, these associations with the presence of cancer persisted in age, deprivation, C-reactive protein, albumin, adjusted calcium, Alk phos and GGT (all P<0.01)." (PMID 20717110, 2010). "The diagnostic/prognostic role of C-reactive protein (CRP) has been sought in some types of cancer; though reports are still divisive." (PMID 19341447, 2009). "Because the C-reactive protein (CRP) is a representative marker for inflammation, CRP has recently been associated with the progression of disease in many cancer types." (PMID 19457231, 2009). "In many studies of cancer patients, it has been noted that elevated CRP levels are associated with tumor size, cancer stage, cancer cachexia, and poor prognosis as independent prognostic indicators." (PMID 19457231, 2009). "In many cancers, it has been reported that chronic inflammation is involved with malignant change, and the risks of cancer are increased when pre-diagnostic CRP levels are high." (PMID 19457231, 2009). "According to a recent systemic review of the association between serum CRP and cancer, CRP concentrations are usually higher in patients with cancer than in healthy controls, but the association seems to be site specific." (PMID 19436291, 2009). "CRP levels have also been used to predict cancer risk, detect cancer recurrence and determine prognosis." (PMID 19948067, 2009). "Elevated serum C-reactive protein (CRP) concentrations have been correlated positively with weight loss in human cancer patients." (PMID 19127266, 2009). "For instance, some studies provided a modest evidence for a positive diagnostic role of CRP in cancer." (PMID 19341447, 2009). "A chronic inflammatory infiltrate was observed in 75% of the cancer specimens and was associated with systemic inflammation (CRP: P=0.01)." (PMID 17088911, 2006).
cancer (continued). "Increased CRP levels are observed in overweight individuals and have been linked with increased cancer risk and elevated levels of cortisol in individuals subjected to psychological stress." (PMID 16469108, 2006). "In cancer patients, the rates of production of IL-6 from isolated PBMCs can be linked to markers of systemic inflammation such as CRP." (PMID 17088911, 2006). "Recently, the systemic inflammatory response, as evidenced by elevated circulating concentrations of C-reactive protein, has been shown to be independently associated with poorer survival in patients with advanced cancer." (PMID 17024120, 2006). "On univariate analysis, stratified by stage, increased Ki-67 labelling index (P<0.05), increased COX-2 expression (P<0.05), C-reactive protein (P<0.05) and adjuvant therapy (P<0.01) were associated with poorer cancer-specific survival." (PMID 17024120, 2006). "On univariate analysis, an elevated C-reactive protein concentration before resection was associated with reduction in cancer-specific survival (P=0.014)." (PMID 17003778, 2006). "In those patients with a UISS risk classified as ‘low’ or ‘intermediate’ (n=91) an elevated C-reactive protein concentration was associated with a decrease in cancer-specific survival (P=0.008)." (PMID 16523196, 2006). "Recently, we have reported that an elevated C-reactive protein was associated with poor cancer-specific survival in patients with bladder cancer independent of tumour stage and grade." (PMID 17024120, 2006). "The results of the present study show that low tumour CD4+ T-lymphocyte infiltration is associated with elevated C-reactive protein concentrations and both predict poor cancer-specific survival." (PMID 15700032, 2005). "A decreased percentage tumour volume of CD4+ T-lymphocytes (P=0.025) and an elevated C-reactive protein (P<0.001) were also associated with poorer cancer-specific survival." (PMID 15700032, 2005). "Within the cancer group, increased levels of CRP (cut-off > 40 mg/ml) in serum were associated with lower levels of TTR (p = 0.08) and RBP (p < 0.05)." (PMID 16225703, 2005). "On multivariate analysis stage (HR 3.37, 95% CI 1.37–8.29, P=0.008), grade (HR 2.01, 95% CI 1.14–3.57, P=0.017) and preoperative C-reactive protein (HR 3.31, 95% CI 1.09–10.09, P=0.035) were independently associated with cancer-specific survival." (PMID 15726119, 2005). "In the present study, both Dukes' stage and C-reactive protein concentrations were independently associated with cancer-specific survival." (PMID 15150596, 2004). "On univariate analysis, increased age (P<0.001), sex (P<0.05), Dukes' stage (P<0.001), elevated circulating C-reactive protein concentrations (P<0.001) and venous invasion (P<0.05) were associated with poor cancer-specific survival." (PMID 15150596, 2004). "Furthermore, the VAI's relation with higher levels of CRP, a widely used inflammation marker in clinical screenings, supports the link between adiposity and cancer risk, as demonstrated in our study." (PMID 39361532, 2025). "A more likely explanation is that inflammation, which increases both YKL-40 and CRP levels, could be the underlying cause, as both biomarkers are linked to cancer risk." (PMID 40188292, 2025). "The fact that CRP, which is regulated by IL-6, rises with IL-6 may be part of the mechanism by which high levels of CRP are associated with poor prognosis in cancer patients." (PMID 40115790, 2025). "High levels of CRP are associated with an increased risk of cancers." (PMID 40563367, 2025). "A large Japanese prospective cohort study demonstrated that individuals in the highest CRP quartile exhibited a 28% increased risk of overall cancer incidence compared to the lowest quartile, with significant associations observed for colorectal, lung, and breast cancer development." (PMID 40563367, 2025).